MIR579 (microRNA 579)
Synonyms: hsa-mir-579; MIRN579
Gene: MicroRNA gene on chromosome 5 (32,394,378 to 32,394,475, reverse strand). Ensembl gene ENSG00000207956.
Homologues: Orthologues: chimpanzee ptr-mir-579 (100% identical), macaque mml-mir-579 (86% identical). Paralogues in human: MIR548H3 (59% identical), MIR548K (57% identical), MIR548Z (56% identical), MIR548AY (55% identical), MIR548AZ (55% identical), MIR548AA1 (54% identical), MIR548AN (53% identical), MIR548X2 (53% identical), MIR548S (52% identical), MIR548F1 (51% identical), MIR548N (51% identical), MIR548AX (50% identical), and 13 more.
Diseases named in the same sentence as MIR579 in open-access papers:
MIR579 is named in the same sentence as 1 disease in open-access papers, as found by Europe PMC text mining. Sharing a sentence is not in itself a finding about the gene and the disease.
MIR579 shares sentences with these, for which no sentence is quoted: Anxiety (1 paper).